MARCHF11 (membrane associated ring-CH-type finger 11)
Description:
E3 ubiquitin-protein ligase that mediates polyubiquitination of CD4. E3 ubiquitin ligases accept ubiquitin from an E2 ubiquitin-conjugating enzyme in the form of a thioester and then directly transfer the ubiquitin to targeted substrates. May play a role in ubuquitin-dependent protein sorting in developmenting spermatids.
Synonyms: MARCH-XI; MARCH11; RNF226
Tractability: Antibody: UniProt predicts a signal peptide or a membrane-spanning region.
Gene: Protein-coding gene on chromosome 5 (16,067,139 to 16,180,762, reverse strand). Ensembl gene ENSG00000183654.
Subcellular location: Cytoplasmic vesicle membrane
Gene Ontology:
Molecular function: ubiquitin-protein transferase activity; ubiquitin protein ligase activity; zinc ion binding
Biological process: protein ubiquitination
Cellular component: cytoplasmic vesicle membrane
Genetic constraint (gnomAD): Loss-of-function variants: 29 observed, 31.6 expected, observed/expected ratio (o/e) 0.92, 90% interval 0.68 to 1.25. The synonymous counts are far from expectation, so gnomAD's model fits this gene poorly and the ratio says little. Missense variants: 482 observed, 462.24 expected, observed/expected ratio (o/e) 1.04, 90% interval 0.97 to 1.12. Synonymous variants: 233 observed, 186.76 expected, observed/expected ratio (o/e) 1.25, 90% interval 1.12 to 1.39.
Homologues: Orthologues: chimpanzee MARCHF11 (99% identical), macaque MARCHF11 (96% identical), pig MARCHF11 (92% identical), mouse Marchf11 (85% identical), rat Marchf11 (85% identical), dog MARCHF11 (77% identical), rabbit MARCHF11 (71% identical), guinea pig MARCHF11 (55% identical), tropical clawed frog marchf11 (51% identical), zebrafish marchf11 (40% identical). Paralogues in human: MARCHF4 (41% identical), MARCHF9 (39% identical), MARCHF1 (17% identical), MARCHF8 (17% identical), MARCHF3 (14% identical), MARCHF2 (13% identical).
Diseases named in the same sentence as MARCHF11 in open-access papers:
MARCHF11 is named in the same sentence as 7 diseases in open-access papers, as found by Europe PMC text mining. Sharing a sentence is not in itself a finding about the gene and the disease.
MARCHF11 shares sentences with these, for which no sentence is quoted: neuroblastoma (2 papers); cancer (1); endometriosis (1); infection (1); neuroendocrine tumors of (1); non-small cell lung carcinoma (1); Pleural effusion (1).